PGA5 (pepsinogen A5)
Description:
Shows particularly broad specificity; although bonds involving phenylalanine and leucine are preferred, many others are also cleaved to some extent.
Synonyms: Pg5
Tractability: Small molecule: a high-quality ligand is known; it belongs to a druggable protein family. Antibody: UniProt places it where antibodies can reach, with medium confidence; UniProt predicts a signal peptide or a membrane-spanning region; its Gene Ontology location is reachable by antibodies, with medium confidence. PROTAC: a small molecule that binds it is known. Other modalities: an approved drug acts on it.
Target class: Aspartic protease; Aspartic protease A1A subfamily; Protease; Enzyme; Aspartic protease AA clan
Gene: Protein-coding gene on chromosome 11 (61,241,175 to 61,251,444, forward strand). Ensembl gene ENSG00000256713.
Subcellular location: Secreted
Pathways (Reactome):
Metabolism of proteins: Surfactant metabolism
Gene Ontology:
Molecular function: aspartic-type endopeptidase activity
Biological process: proteolysis
Cellular component: extracellular exosome; multivesicular body lumen; extracellular region
Genetic constraint (gnomAD): Loss-of-function variants: 18 observed, 15.86 expected, observed/expected ratio (o/e) 1.13, 90% interval 0.78 to 1.66. The upper end of that interval is the gene's LOEUF score, 1.66, which puts it in group 6 of 6, group 1 being the genes least tolerant of losing a copy. Missense variants: 199 observed, 228.89 expected, observed/expected ratio (o/e) 0.87, 90% interval 0.77 to 0.98. Synonymous variants: 76 observed, 87.48 expected, observed/expected ratio (o/e) 0.87, 90% interval 0.72 to 1.05.
Homologues: Orthologues: macaque PGA4 (94% identical), pig PGA5 (83% identical), dog PGA (81% identical), tropical clawed frog pga4 (68% identical), Drosophila melanogaster Bace (43% identical), Drosophila melanogaster CG17134 (41% identical), Drosophila melanogaster CG33128 (39% identical), Drosophila melanogaster CG6508 (39% identical), Caenorhabditis elegans asp-1 (34% identical), Caenorhabditis elegans asp-16 (34% identical), Caenorhabditis elegans asp-17 (33% identical), Caenorhabditis elegans asp-18 (32% identical), and 6 more. Paralogues in human: PGA4 (99% identical), PGA3 (99% identical), CTSE (54% identical), PGC (50% identical), CTSD (45% identical), NAPSA (41% identical), REN (35% identical), BACE1 (30% identical), BACE2 (30% identical).
Diseases named in the same sentence as PGA5 in open-access papers:
PGA5 is named in the same sentence as 24 diseases in open-access papers, as found by Europe PMC text mining. Sharing a sentence is not in itself a finding about the gene and the disease. The quoted sentences say what the papers report.
gastric cancer (3 papers, 2019 to 2025). A primary or metastatic malignant neoplasm involving the stomach. "PGA3 is highly expressed in bone metastases of gastric cancer, indicating poor survival, and PGA5 expression can induce changes related to tumor progression and epithelial–mesenchymal transition." (PMID 41009814, 2025). "PGA3 and PGA5 are mainly expressed in ovarian cancer and lung cancer, while PGA4 is mainly expressed in lung cancer and gastric cancer cell lines." (PMID 33067881, 2020).
Barrett esophagus (2 papers, 2016 to 2020). Esophageal lesion lined with columnar metaplastic epithelium which is flat or villiform. "PGA3, PGA4, and PGA5 encode pepsinogen A (PGA), and the differential expression of PGA3, PGA4, and PGA5 is related to the pre-neoplastic nature in patients with Barrett’s esophagus." (PMID 27855662, 2016).
endometrial carcinoma (2 papers, 2020). A malignant tumor arising from the epithelium that lines the cavity of the uterine body. "It is worth noticed that all PGC, PGA3, and PGA5 genes had a certain degree of mutation in endometrial carcinoma, which is a tumor with high global mutation rate." (PMID 33067881, 2020). "PGA5 was associated with good prognosis of cancer patients such as kidney renal clear cell carcinoma and kidney renal papillary cell carcinoma, while lung squamous cell carcinoma, prostate adenocarcinoma, and endometrial carcinoma are associated with poor prognosis of cancer patients." (PMID 33067881, 2020).
bladder urothelial carcinoma (1 paper, 2020). "PGA3, PGA4, and PGA5 showed more copy number amplification in lung adenocarcinoma, esophageal carcinoma, kidney chromophobe, and copy number reduction in bladder urothelial carcinoma, lung squamous cell carcinoma, rectum adenocarcinoma, and cholangiocarcinoma." (PMID 33067881, 2020).
tumor (4 papers, 2020 to 2025). "Both these genes were oncogenes, and downregulated genes such as ATP4A, ATP4B, PGA3, PGA4, and PGA5 were reported tumor suppressors in GC." (PMID 39283078, 2024). "(C) Violin plots of single-cell sequencing data showing expression levels of Gkn1, Tff1, Tff2, Cym, Pgc, Pga5, and Pou2f3 transcripts in BPN tumor clusters 1–3 and highlighting key drug-mediated cell-identity changes." (PMID 33821796, 2021).
cancer (3 papers, 2015 to 2024). A tumor composed of atypical neoplastic, often pleomorphic cells that invade other tissues. "PGs expression was significantly related to the activation or inhibition of many signal transduction pathways, in which PGC and PGA5 are more likely to be associated with cancer‐related pathways." (PMID 33067881, 2020). "The mutation rates of PGA3, PGA4, and PGA5 in all cancer lines were low and less than 2%." (PMID 33067881, 2020). "Using the count data of 33 human tumors covered by TCGA, we analyzed the differential expression of PG family genes including PGC, PGA3, PGA4, and PGA5 in different cancers at the overall level based on continuous variable analysis." (PMID 33067881, 2020). "Our findings suggest that PGC and PGA5 had different effects on the prognosis of many kinds of cancers and they may be used as predictors of the prognosis in different cancers." (PMID 33067881, 2020). "PGA3, PGA4, and PGA5 were expressed in most normal tissues, but decreased in cancer tissues." (PMID 33067881, 2020). "PGA3, PGA4, and PGA5 are mainly involved in K‐RAS signaling pathway, bile acid metabolism, mitotic G2 M phase, and other cancer‐related pathways." (PMID 33067881, 2020). "The data of 21 kinds of cancers from The Protein Atlas showed that the expression of PGA3, PGA4, and PGA5 could not be detected in any cancer tissues." (PMID 33067881, 2020).
PGA5 also shares sentences with these, for which no sentence is quoted: breast carcinoma (3 papers); cholangiocarcinoma (1); colon adenocarcinoma (1); esophageal carcinoma (1); frontotemporal dementia (1); HCMV infection (1); hepatocellular carcinoma (1); infection (1); kidney chromophobe (1); lung adenocarcinoma (1); lung carcinoma (1); lung squamous cell carcinoma (1); ovarian carcinoma (1); prostate adenocarcinoma (1); rectum adenocarcinoma (1); stomach adenocarcinoma (1); thyroid carcinoma (1); uterine corpus endometrial carcinoma (1).